PAX4 (paired box 4)
Description:
DNA-binding transcription factor that plays a central role in the differentiation and development of type B pancreatic cells, which are located within the pancreatic islets of Langerhans responsible for the production and release of insulin (By similarity). Mainly acts as a transcription repressor that binds to a common element in the glucagon, insulin and somatostatin promoters and inhibits their expression (By similarity). Prevents differentiation of type A pancreatic cells, probably by repressing expression of ARX (By similarity). Competes with another transcription factor, PAX6, for this same promoter binding site (By similarity). Also plays a key role in intestinal enteroendocrine cell differentiation by (1) directly promoting differentiation of enterochromaffin cells and (2) preventing differentiation of other intestinal enteroendocrine cell types. Prevents differentiation of other intestinal enteroendocrine cell types by repressing the expression of ARX, the master transcription factor for intestinal type-L, -N, -D, -I and -G enteroendocrine cell differentiation. [Isoform 2]: Isoform 2 appears to be a dominant negative form antagonizing PAX4 transcriptional activity.
Synonyms: MODY9; KPD
Tractability: No criterion of Open Targets' tractability assessment is met for any kind of drug.
Gene: Protein-coding gene on chromosome 7 (127,610,292 to 127,618,142, reverse strand). Ensembl gene ENSG00000106331.
Subcellular location: Nucleus; Chromosome
Pathways (Reactome):
Developmental Biology: Regulation of gene expression in endocrine-committed (NEUROG3+) progenitor cells
Gene Ontology:
Molecular function: DNA-binding transcription repressor activity, RNA polymerase II-specific; sequence-specific double-stranded DNA binding; DNA binding; DNA-binding transcription factor activity, RNA polymerase II-specific; RNA polymerase II cis-regulatory region sequence-specific DNA binding; double-stranded DNA binding
Biological process: animal organ morphogenesis; brain development; forebrain development; regulation of transcription by RNA polymerase II; retina development in camera-type eye; sensory organ development; type B pancreatic cell differentiation; animal organ development; negative regulation of DNA-templated transcription; negative regulation of transcription by RNA polymerase II; regulation of DNA-templated transcription
Cellular component: chromatin; nucleoplasm; nucleus; chromosome
Genetic constraint (gnomAD): Loss-of-function variants: 33 observed, 41.8 expected, observed/expected ratio (o/e) 0.79, 90% interval 0.6 to 1.06. The upper end of that interval is the gene's LOEUF score, 1.06, which puts it in group 4 of 6, group 1 being the genes least tolerant of losing a copy. Missense variants: 459 observed, 443.21 expected, observed/expected ratio (o/e) 1.04, 90% interval 0.96 to 1.12. Synonymous variants: 174 observed, 171.79 expected, observed/expected ratio (o/e) 1.01, 90% interval 0.89 to 1.15.
Gene-disease validity (ClinGen):
ClinGen rates the evidence that PAX4 causes each of these diseases.
monogenic diabetes (autosomal dominant): Refuted. Diabetes mellitus that is caused by mutations in a single gene.
Homologues: Orthologues: chimpanzee PAX4 (99% identical), macaque PAX4 (94% identical), pig PAX4 (82% identical), rabbit PAX4 (79% identical), dog PAX4 (78% identical), rat Pax4 (75% identical), mouse Pax4 (75% identical), guinea pig PAX4 (74% identical). Paralogues in human: PAX7 (38% identical), PAX3 (36% identical), PAX2 (31% identical), PAX5 (30% identical), PAX8 (30% identical), PAX1 (28% identical), PAX9 (26% identical), PAX6 (21% identical), EVX2 (18% identical), ALX4 (17% identical), ARX (17% identical), NOBOX (16% identical), and 38 more.
Diseases named in the same sentence as PAX4 in open-access papers:
PAX4 is named in the same sentence as 49 diseases in open-access papers, as found by Europe PMC text mining. Sharing a sentence is not in itself a finding about the gene and the disease. The quoted sentences say what the papers report.
diabetes (45 papers, 2012 to 2025). "Polymorphisms/mutations in the diabetes-linked paired/homeodomain transcription factor Pax4 have been associated with several forms of diabetes, including T1D, T2D, and monogenic diabetes." (PMID 39857806, 2025). "•Homozygous loss-of-function variants in PAX4 are a novel genetic cause of transient neonatal diabetes." (PMID 40614820, 2025). "This differs from observations in rodent Pax4 KO models that have complete loss of beta cells resulting in permanent neonatal diabetes and postnatal death." (PMID 40614820, 2025). "More than a decade after the initial report, only a few additional studies—mainly in Asian populations—have confirmed the involvement of PAX4 mutations in monogenic diabetes." (PMID 41153735, 2025). "Overall, EPs carrying PAX4 diabetes risk alleles demonstrated a bioenergetic switch from glycolysis to oxidative phosphorylation." (PMID 37777536, 2023). "Taken together, these findings are insufficient to provide support for the p.Tyr186X variant as the cause of monogenic diabetes in this family but are consistent with the PAX4 variant being associated with decreased pancreatic beta cell function." (PMID 37777536, 2023). "In the human population, mutations in the PAX4 gene are found to be associated with both type 1 and type 2 diabetes mellitus (T1D and T2D), and maturity onset diabetes of the young (MODY)." (PMID 37175989, 2023). "Mutations in Pax4 that cause an impaired Pax4 function are associated with diabetes pathogenesis in humans." (PMID 37175989, 2023). "Our observations are consistent with rare PAX4 alleles resulting in haploinsufficiency being insufficient to cause fully penetrant monogenic diabetes but increasing the risk for T2D." (PMID 37777536, 2023). "Despite the incomplete knowledge of the molecular basis of PAX4 mutations causing diabetes, new evidence has shed a light on possible treatments." (PMID 36361703, 2022). "PAX4 is a key diabetes mellitus (DM) susceptibility gene, which is associated with many different types of DM, including T1DM, T2DM, maturity onset diabetes of the young 9 (MODY9) and ketosis prone diabetes." (PMID 29950431, 2018). "PAX4 is linked to the susceptibility of β-cells to apoptosis, leading to diabetes, and is found to be significantly differentially expressed within a T2D cohort of adult islets." (PMID 30007277, 2018). "The functional importance of PAX4 DBDs is clearly established by the fact that the majority of PAX4 mutations associated with diabetes are located within these domains." (PMID 28282933, 2017). "The importance of this transcription factor for adequate pancreatic islets functionality has been manifested by the association of mutations in PAX4 with the development of diabetes, independently of its etiology." (PMID 28282933, 2017). "One of the best characterized diabetes-linked mutations of PAX4 is R121W (homolog to R129W in mouse)." (PMID 28282933, 2017). "Pax4 gene mutations have been associated with type 1 and 2 diabetes as well as with ketosis-prone diabetes, suggesting a key role of PAX4 in mature islets." (PMID 26813254, 2016). "Accordingly, overexpression of PAX4 in adult beta cells was shown to block streptozotocin (STZ)-induced hyperglycaemia in mice whereas the diabetes-linked variant PAX4R129W was less efficient." (PMID 26813254, 2016). "Transcriptome profiling was conducted on PAX4 and PAX4R129W islets to highlight PAX4 target genes involved in beta cell health, and those altered by the diabetes-linked mutant variant R129W." (PMID 26813254, 2016). "In summary, we identified variants in BLK, CEL, KLF11, PDX1, and PAX4 that may contribute to various forms of diabetes, including rare MODY subtypes." (PMID 41153735, 2025).
diabetes (continued). "Loss-of-function PAX4 mutations in humans are implicated in diabetes pathogenesis." (PMID 41153735, 2025). "Interestingly, Hu He and collaborators compared the overexpression of Pax4 with the equivalent overexpression of the diabetes-linked mutant variant of Pax4, Pax4R129W." (PMID 39857806, 2025). "PAX4 predominantly exhibits expression in the pancreas during embryonic development, and mutations in the PAX4 gene have been implicated in the development of diabetes mellitus." (PMID 38928435, 2024). "Impaired Pax4 functions, however, make these individuals susceptible to diabetes development." (PMID 37175989, 2023). "This phenotype was confirmed independently in the human beta cell line EndoC-βH1 and could be reversed in donor-derived hiPSC lines through correction of diabetes-associated PAX4 alleles." (PMID 37777536, 2023). "Consequently, PAX4 mutation can be a risk factor contributing to the predisposition of diabetes pathogenesis." (PMID 37175989, 2023). "Pax4 gene mutations are associated with the development of diabetes." (PMID 37175989, 2023). "Knowledge of the molecular basis of PAX4 mutations causing diabetes remains incomplete." (PMID 36361703, 2022). "Furthermore, PAX4 is involved in the differentiation of insulin-producing β- and δ-cells of the pancreas, and certain mutations in PAX4 can lead to the development of severe diabetes mellitus." (PMID 31216190, 2019). "It was found that the expression of NeuroD1-βcellulin reversed diabetes and maintained normoglycaemia, with associated up-regulation of both upstream and downstream β-cell transcription factors, including Pdx1, Pax6, Pax4, Nkx2.2, and Nkx6.1, as seen in the current study." (PMID 27070593, 2016). "As yet, there is no ‘unifying hypothesis’ for the mechanisms triggering beta cell deterioration; deciphering the molecular roadmap regulated by factors such as PAX4—mutations in which are linked to both forms of diabetes—may help identify common pathways." (PMID 26813254, 2016). "Disparity in the impact of pax4 gene mutations on the incidence of diabetes could potentially be rationalized by the outcome of gene-environment interaction, which will dictate fitness of β-cells." (PMID 26503027, 2015). "However, the high frequency of the variants in the population and a lack of cosegregation with diabetes has led to discussion over whether they are causal for diabetes and if PAX4 should be included in diagnostic testing panels for monogenic diabetes." (PMID 37777536, 2023). "A Korean study found that the combination of PAX4 Arg192His and PAX4 Arg192Ser could be considered a strong risk factor for T2D, and having two copies of PAX4 Arg192His variant was related to a 7.0 years earlier onset of diabetes." (PMID 35921062, 2022). "Indeed, mutations associated with decreased activity of the gene encoding PAX4 are linked to type 2 diabetes mellitus (DM), and overexpression of PAX4 in β-cells stimulates their proliferation in both humans and rats." (PMID 41472147, 2025). "Several PAX4 variants have been linked to type 1 diabetes (T1DM), type 2 diabetes (T2DM), ketosis-prone type 2 diabetes (KPD), and monogenic diabetes, first reported in two Thai patients." (PMID 41153735, 2025). "PAX4 missense mutations have also been reported in patients with maturity onset diabetes of the young (MODY), a type of diabetes that resembles adult-onset type 2 diabetes but occurs in juvenile patients." (PMID 38473380, 2024). "The Pax4-expressing transgenic mice are more resistant to STZ-induced β cell destruction and hyperglycemia compared to mice overexpressing a diabetes-linked Pax4 mutant variant Pax4R129W." (PMID 37175989, 2023). "The purpose of this review is to provide a thorough and up-to-date overview of the role of Pax4 in pancreatic β cells and its potential as a therapeutic target for diabetes." (PMID 37175989, 2023). "In our study, we identified deleterious frameshift duplication in PAX4 in a family having both diabetes and POAG." (PMID 36833422, 2023).
diabetes (continued). "Several genes were found to be enriched, however hepatocyte nuclear factor 4 alpha (HNF4A) and paired box 4 (PAX4) were found to be strongly related to the diabetes onset pathway." (PMID 36037214, 2022). "From this study, we conclude that the misexpression of Pax4 in D cells appears sufficient to convert these into functional beta-like cells, thus opening new research avenues in the context of diabetes research." (PMID 35573999, 2022). "For example, PAX4 is involved in regulating pancreatic β-cell proliferation and survival in diabetes." (PMID 34162761, 2021). "PAX4 displays both immune and regenerative properties, and combination with downstream targets offers a new prospective in diabetes treatment." (PMID 34162761, 2021). "We excluded the remaining MODY genes (CEL, PDX1, PAX4, BLK, KLF11, NEUROD1) from this analysis since either very few missense mutations in these genes have been associated with early onset diabetes or the genetic evidence for association is limited." (PMID 29207974, 2017). "We found that PAX4 blunts DNA damage in two models of experimental diabetes, pointing to a general protective mechanism, possibly through preserved ER homeostasis, implicating CALR." (PMID 26813254, 2016). "Diabetes in Cocker Spaniels showed an association with three SNPs from three different genes: MTTL1 (rs24305581), PAX4 (rs22302353) and INS (rs22686871) and in the miniature Dachshund there was a single association with HNF4A (rs8804236)." (PMID 26401325, 2014). "The expression of Pax4 leads to oversized islets and is eventually accompanied by beta cell dysfunction and diabetes." (PMID 23382704, 2013). "It is interesting to remind that, in contrast to Pdx1, the sole expression of Pax4 is sufficient to reprogram alpha-cells into insulin-producing beta-cells that counter chemically induced diabetes." (PMID 23326678, 2012). "Remarkably, the sole misexpression of Pax4 in glucagon-expressing cells is able to induce their regeneration, endow these with beta-cell features, and thereby counter chemically induced diabetes." (PMID 22717987, 2012). "The forced expression of Pax4 in glucagon-expressing alpha-cells is able to convert these into functional beta-cells that counter chemically induced diabetes in mice." (PMID 23326678, 2012). "Along the same line of evidence, the sole forced expression of Pax4 in glucagon-producing cells is able to reprogram alpha-cells into functional beta-cells that can counter chemically induced diabetes." (PMID 23326678, 2012). "Upregulation of PAX4 promotes β-cell survival and proliferation, while ectopic expression of PAX4 in α- or δ-cells can generate functional β-like cells, improving glucose regulation in experimental diabetes models." (PMID 41153735, 2025). "Reduced PAX4 expression in hPS cells may affect their differentiation into insulin-producing β-cells negatively, which could be crucial for diabetes studies." (PMID 40666289, 2025). "In the present study, we provide evidence that PDAC-associated diabetes is distinguished by a global downregulation of key islet hormones (INS, GCG) as well as β-cell-enriched transcription factors such as MAFA and PAX4, and hormone receptors such as GCGR, SSTR3 and SSTR5." (PMID 40244011, 2025). "Recent studies of large population samples have not confirmed the role of BLK, KLF11, and PAX4 gene variants in the development of monogenic diabetes." (PMID 39859454, 2025). "PAX4 is one of the important candidate genes of diabetes and may be involved in regulation in the optic nerve tissue." (PMID 36833422, 2023). "Here we present detailed human in vivo and in vitro studies on two different PAX4 coding alleles, the East Asian population enriched p.Arg192His and a novel protein-truncating variant (PTV) p.Tyr186X identified in a Singapore family with early onset diabetes." (PMID 37777536, 2023).
diabetes (continued). "Of note, the family members with diabetes who do not carry the PAX4 variant all displayed evidence of insulin resistance (HOMA-IR > 2) and low DI, consistent with T2D." (PMID 37777536, 2023). "Additionally, ectopic expression of Pax4 in pancreatic islet α cells or δ cells has been found to generate functional β-like cells that can improve blood glucose regulation in experimental diabetes models." (PMID 37175989, 2023). "Furthermore, the ectopic expression of Pax4 in alpha cells led to restoring a functional beta cell mass and to diabetes cure in animals that were chemically depleted of beta cells." (PMID 37008919, 2023). "Family member II-3, who does not have diabetes and does not carry the p.Tyr186X variant, has the highest beta cell function as measured by the DI whilst those carrying the PAX4 variant (II-11 and II-7) have markedly reduced function." (PMID 37777536, 2023). "The selective inhibition of Arx in alpha cells or ectopic expression of Pax4 leads to the regeneration of insulin-producing beta cells arising from alpha cells which results in the alleviation of diabetes symptoms in mice whose beta cells have been chemically damaged." (PMID 37008919, 2023). "Therefore, Pax4 represents a promising therapeutic target for the protection and regeneration of β cells in the treatment of diabetes." (PMID 37175989, 2023). "Our work thus demonstrates that Pax4 gene modulation could represent an interesting path for reprogramming intestinal cells into beta-like cells, a result of great potential for diabetes research." (PMID 35573999, 2022). "Importantly, mice misexpressing Pax4 in alpha-cells were found able to recover from several cycles of chemically-induced diabetes as a result of beta-like cell neogenesis." (PMID 35573999, 2022). "Remarkably, Pax4 expression levels also increase in the STZ mouse model of diabetes, and in vivo ectopic overexpression of this factor enhances β-cell resistance to STZ, as well as against an autoimmune attack in a mouse model of experimental autoimmune diabetes." (PMID 33921851, 2021). "Altogether these data pinpoint at PAX4 as an important target for novel regenerative therapies for diabetes treatment, aiming at the preservation of the remaining β-cells in parallel to the stimulation of their proliferation to replenish the β-cell mass lost during the progression of the disease." (PMID 28282933, 2017). "Interestingly, among these five putative regulators of PAX4, four of them are established Maturity-Onset Diabetes of the Young (MODY) genes: HNF4α-MODY1, HNF1α-MODY3, PDX1-MODY4 and NEUROD1-MODY6." (PMID 28282933, 2017). "Remarkably, the forced expression of Pax4 in glucagon+ cells in vivo was found to induce their regeneration and subsequent conversion into functional beta-like cells that can counter chemically-induced diabetes." (PMID 22717987, 2012). "Thus, PAX4 is a promising therapeutic target for β-cell protection and regeneration in diabetes." (PMID 41153735, 2025). "Notably, PAX4 mutations not only render individuals vulnerable to T1D and MODY, but also increase the risk for T2D development, which supports the importance of β cell function in the etiology of all forms of diabetes." (PMID 37175989, 2023). "Whilst our investigation of the impact of a novel variant predicted to result in a loss of PAX4 function (p.Tyr186X) demonstrated that PAX4 haploinsufficiency is insufficient to cause monogenic diabetes, it was consistent with a negative impact on beta cell function." (PMID 37777536, 2023). "This substitution, replacing a polar amino acid with a non-polar one, was predicted to impair the inhibitory activity of PAX4 on the INS and GCG promoters, leading to hyperglycemia and diabetes." (PMID 41153735, 2025).